LINC02265 (long independently transcribed non-coding RNA 2265)
Gene: Long non-coding RNA gene on chromosome 4 (40,307,184 to 40,330,422, forward strand). Ensembl gene ENSG00000249241.
Diseases named in the same sentence as LINC02265 in open-access papers:
LINC02265 is named in the same sentence as 1 disease in open-access papers, as found by Europe PMC text mining. Sharing a sentence is not in itself a finding about the gene and the disease.
LINC02265 shares sentences with these, for which no sentence is quoted: hypothyroidism (1 paper).